CRP (C-reactive protein)
Diseases named in the same sentence as CRP in open-access papers (continued):
Sharing a sentence is not in itself a finding about the gene and the disease.
pharyngitis (20 papers, 2016 to 2025). Inflammation of the throat most often caused by viral and bacterial infections. "One year after the first admission, he presented with a one day-history of fever, in association with pharyngitis and elevation of acute-phase reactants (CRP 167 mg/L; PCT 0.27 ng/mL)." (PMID 39295697, 2024). "The specificity of CRP testing to identify pharyngitis caused by GAS is poor as CRP can be raised in other infections and inflammatory processes." (PMID 31889507, 2020). "The use of point-of-care testing (.e.g., C-reactive protein) for and rapid antigen diagnostic tests) for RTIs including acute sore throat caused by Group A streptococcal infections has been growing for appropriate clinical decisions on antimicrobial therapy in primary care." (PMID 36139938, 2022). "Pharyngitis, high fever, marked fatigue; pronounced tonsillar hypertrophy and cervical lymphadenopathy; CRP usually <100 mg/L but can be elevated." (PMID 40933813, 2025). "In this study, we aimed to analyze how the Centor score associated with rapid antigen test findings and C reactive protein (CRP) levels in Finnish children with sore throat." (PMID 39528865, 2024). "On physical examination, aphthous stomatitis and pharyngitis were denoted, and the blood sample revealed a new increase in inflammatory markers (CRP 158.01 mg/L; PCT 10.66 ng/mL)." (PMID 39295697, 2024). "Our patient presented with fever, migratory oligoarthritis, markedly elevated inflammatory parameters (C-reactive protein and erythrocyte sedimentation rate), and a history of recent pharyngitis." (PMID 39618634, 2024). "The rate of those with CRP ≤9.8 mg/dL in the Strep Pharyngitis group was 24.6 (2.7–222.4) times higher than that in the PFAPA group." (PMID 37428978, 2023). "Six patients with inflammatory fever presented with pharyngitis/amygdalitis (4/6), oral aphthous ulcer (2/6), digestive symptoms (3/6), developmental delay (4/6) and elevated C-reactive protein levels (6/6) during fever." (PMID 35897075, 2022). "The highest CRP results were observed in patients with KD (112.3 mg/L, p < 0.01), while procalcitonin was the highest in patients with S. pyogenes pharyngitis (2.37 μg/L, p = 0.44)." (PMID 34682194, 2021). "Studies on pharyngitis and CRP seems scarce; however, a study found a higher mean for individuals with streptococcus C than A infection, but another study highlighted that it may help to rule out streptococcal infection in pharyngitis adult cases." (PMID 37873776, 2023). "Almost one third (28.5%) of the patients with sore throat diagnosed in 2013 had a CRP taken." (PMID 27887585, 2016). "WBC, CRP, and PCT were higher in those patients with pharyngitis compared to asymptomatic controls, including those carrying group A Streptococcus (GAS) asymptomatically." (PMID 39441193, 2024). "Furthermore, earlier data on CRP in differentiating GAS from other aetiologies of pharyngitis does not support its use." (PMID 36163516, 2022).
small cell lung carcinoma (20 papers, 1989 to 2025). Small cell lung cancer (SCLC) is a highly aggressive malignant neoplasm, accounting for 10-15% of lung cancer cases, characterized byrapid growth, and early metastasis. "Recently, Dr. Shao and her colleague found that the high CRP level was associated with the poor outcome for combined small cell lung cancer." (PMID 27303917, 2016). "In a retrospective study of limited-disease small-cell lung cancer patients undergoing thoracic chemoradiotherapy, patients with a high CRP level showed longer OS than those with lower CRP level (median 20 vs. 14 months, respectively, p = 0.025)." (PMID 31443339, 2019). "We have measured the serum concentration of the acute phase reactant, C-reactive protein (CRP), in 20 patients with histologically proven small cell lung cancer undergoing their first pulse of induction cytotoxic chemotherapy." (PMID 2544225, 1989). "Although an association was observed between C-reactive protein and small cell lung cancer, this finding was not corroborated by sensitivity analyses using MRAID or co-localization testing." (PMID 41204557, 2025). "Both pro-CRP and CEA are autonomous growth factors for the treatment of small-cell lung cancer." (PMID 35572829, 2022). "Although the mechanisms by which C-reactive protein and albumin support tumor growth are not well known, the high ratio of these proteins in peripheral blood was shown to have a negative prognostic value in small cell lung carcinoma." (PMID 33276524, 2020).
ventilator-associated pneumonia (20 papers, 2006 to 2025). Serious INFLAMMATION of the LUNG in patients who required the use of PULMONARY VENTILATOR. "The main purpose of this study was to investigate the dynamics of pentraxin 3 (PTX3) compared with procalcitonin (PCT) and C-reactive protein (CRP) in patients with suspicion of ventilator-associated pneumonia (VAP)." (PMID 29861799, 2018). "In that study, daily CRP measurements after antibiotic prescription were useful in the identification, as early as day 4, of ventilator-associated pneumonia patients with poor outcome." (PMID 17723153, 2007). "• Survival is directly related to decreasing levels of procalcitonin and C-reactive protein in ventilator-associated pneumonia." (PMID 16956405, 2006). "In the later stages of treatment (seventh day of hospital stay), the culture of lower respiratory tract secretions indicated the growth of K pneumoniae, presence of C-reactive protein, an elevated procalcitonin index compared to before, and appearance of ventilator-associated pneumonia." (PMID 33120803, 2020). "Elevated serum PCT and CRP were associated with community-acquired pneumonia and ventilator-associated pneumonia (VAP)." (PMID 30285748, 2018). "Elevated CRP concentrations have been successfully used as a biomarker of infection in septic patients with community-acquired pneumonia (CAP) or ventilator-associated pneumonia (VAP) and as a marker of bacterial load and appropriate antibiotic therapy." (PMID 36836567, 2023). "C-reactive protein (CRP) and procalcitonin (PCT) had been reported be a prognostic marker of outcome during severe CAP and ventilator-associated pneumonia (VAP)." (PMID 35196337, 2022). "In a previous study, our group assessed the value of daily measurements of CRP, WCC and body temperature after the prescription of antibiotics in ventilator-associated pneumonia patients." (PMID 17723153, 2007). "In addition, it has been described, in ventilator associated pneumonia (VAP), a good correlation between bacterial load and CRP levels, as well as between the adequacy of antibiotic therapy and changes of CRP concentration overtime." (PMID 21762483, 2011). "CRP, C-reactive protein; PCT, procalcitonin; PSP, pancreatic stone protein; VAP, ventilator-associated pneumonia." (PMID 37893050, 2023). "For patients with suspected ventilator-associated pneumonia (VAP), the 2016 ATS/IDSA guidelines recommend using clinical criteria alone, rather than combining those criteria with procalcitonin (PCT) or C-reactive protein (CRP) to decide whether to start antibiotics." (PMID 29861799, 2018). "The aim of this study was to determine the diagnostic and prognostic roles of C-reactive protein (CRP) and tumor necrosis factor-alpha (TNF-α) in differentiating between ventilator-associated pneumonia and SIRS without infectious etiology." (PMID 28469676, 2016).
abdominal aortic aneurysm (19 papers, 2004 to 2025). Enlargement and ballooning of the vessel that supplies arterial blood to the abdomen, pelvis and legs. "Reportedly, CRP is an independent risk factor in detection of vascular inflammation was associated with abdominal aortic aneurysm progression but few studies in TAAD." (PMID 37378402, 2023). "Interestingly, CRP has also been associated with abdominal aortic aneurysm pathophysiology." (PMID 30988354, 2019). "We investigated the effects of C-reactive protein (CRP) deposition on the vessel walls in abdominal aortic aneurysm (AAA) by analyzing spatially resolved changes in gene expression." (PMID 39737187, 2024). "The association between abdominal aortic aneurysms and inflammation is previously studied and some markers such as white blood cell (WBC), C-reactive protein (CRP), interleukin 6, and albumin are shown to be responsible." (PMID 36195877, 2022). "C-reactive protein (CRP) levels are elevated in patients with abdominal aortic aneurysms (AAA)." (PMID 37753091, 2023). "Moreover, the strong correlation between serum Cat S levels and high-sensitivity C-reactive protein (hs-CRP) or Cys-C was proved in many diseases like abdominal aortic aneurysm patients." (PMID 27058412, 2016). "The monomeric form of C-reactive protein (mCRP) is deposited in damaged cardiovascular organs and aggravates the prognosis; however, it is unknown whether mCRP is deposited in the degenerated aorta of abdominal aortic aneurysm (AAA)." (PMID 34428207, 2021). "The CRP-to-albumin ratio (CAR) was found a better indicator of the inflammatory process than either marker alone in cardiovascular disease development and also the progression of abdominal aortic aneurysms." (PMID 36195877, 2022). "Other investigators have failed to observe increased CRP levels among asymptomatic patients with abdominal aortic aneurysm." (PMID 15482602, 2004).
adenoma (19 papers, 2010 to 2025). A neoplasm arising from the epithelium. "In our present observations, the CRP-adenoma association was more evident with larger and multiple adenomas than with smaller and single adenomas." (PMID 28667300, 2017). "Plasma CRP level was positively associated with higher adenoma prevalence in all subjects (OR 1.30; 95% CI 0.94–1.79 for the highest versus lowest quartile; P trend = 0.031)." (PMID 28667300, 2017). "We further examined the association between plasma CRP level and colorectal adenoma by the size and number of adenomas." (PMID 28667300, 2017). "CRP levels were different between all groups and increased from control via adenoma to the carcinoma group." (PMID 35160173, 2022). "B. dorei correlated with levels of C-reactive protein (CRP), a marker for acute inflammation, suggesting a potential role in adenoma formation." (PMID 34205378, 2021). "During adenoma-carcinoma development, a progressive increase in interleukin-8 (IL-8), CRP, and MMP-9 occurs." (PMID 29929486, 2018). "We also observed that CRP and sTNFR-II increased with the adenoma-carcinoma sequence (CRP: JT = 36, 401.5, P < 0.001, sTNFR-II: JT = 37, 225.5, P < 0.001)." (PMID 30157754, 2018). "Plasma C-reactive protein (CRP) and soluble tumor necrosis factor II (sTNFR-II) displayed significant differences among the four study groups and increased with adenoma-carcinoma sequence." (PMID 30157754, 2018). "The OR of adenoma for the highest compared to the lowest quartile of plasma CRP was 1.12 (95% CI 0.80–1.56), with P trend = 0.25, in overall subjects and 1.22 (95% CI 0.80–1.88), with P trend = 0.11, in men after adjusting for BMI." (PMID 28667300, 2017). "A logistic regression model was used to compute odds ratios (OR) and 95% confidence intervals (CI) of adenoma according to quartile of plasma CRP." (PMID 28667300, 2017). "The combination of CEA + IL-8 recognized six and the combination of CEA + CRP detected five of 34 adenoma patients correctly." (PMID 22954206, 2012). "For the non-advanced adenomas, one patient, which was positive detected by CEA + IL-8 was also detected by CEA + CRP, for the advanced adenomas also one positive patient overlapped between both marker combinations." (PMID 22954206, 2012). "Tissue inhibitor of metalloproteinases-1 showed the largest AUC for detection of advanced adenoma and CRP showed the largest AUC for detection of CRC among the four tested blood markers." (PMID 22454079, 2012). "Similar results showed CRP with low median levels of 2,020 ng/mL for adenoma patients and higher levels of 4,018 ng/mL for carcinoma patients and 2,086 ng/mL for healthy controls (both P > 0.05)." (PMID 22954206, 2012). "Similarly, it was confirmed that CRC-associated bacteria were changed with the degree of malignancy and inflammatory factors (Plasma C-reactive protein and soluble tumor necrosis factor II) increased across the adenoma-carcinoma sequence." (PMID 35935780, 2022). "These bacteria, as well as plasma CRP and sTNFR-II, changed along the adenoma-carcinoma sequence." (PMID 30157754, 2018). "In our study, CRP and sTNFR-II tended to increase along the adenoma-carcinoma sequence." (PMID 30157754, 2018). "Since our samples were collected at the end of B(a)P and diet exposure, by which time the adenomas were fully developed and the low CRP levels at the high B(a)P dose group signifies reduced systemic anti-inflammatory response and the immunosurveillance is compromised." (PMID 26959117, 2016). "Whether the association with either circulating CRP levels or inflammatory scores varied by adenoma sites was not consistent." (PMID 32051482, 2020). "Whether this applies to multiple adenomas with multiple CRP positive foci is yet unclear." (PMID 23024866, 2012). "However, the CRP-positive foci indicate that in cases with multiple adenomas, minute foci of adenomas may be present, also in the remnant liver." (PMID 23024866, 2012).
adenoma (continued). "Six genes (SAA2, SAA1, CRP, SAA3P, PLA2G2A, and APOA4) listed in the heat map also indicated that the expression of PLA2G2A was limited to the adenoma tissue, following the violin plot results." (PMID 38201587, 2023). "However, the confidence intervals were wide and low statistical power may have been the reason for not detecting the association of hs-CRP levels and advanced adenoma." (PMID 34439443, 2021). "Circulating CRP levels appeared to be positively associated with the prevalence of colorectal adenoma in those with a larger adenoma (≥5 mm) but not in those with smaller adenoma (<5mm), and also in those with multiple adenomas (≥2) but not in those with a single adenoma." (PMID 28667300, 2017). "Taken together, our results showed that blood levels of sCD26, CRP and TIMP-1 were different in CRC patients compared with participants free of neoplasms, and TIMP-1 levels were also elevated in advanced adenoma patients." (PMID 22454079, 2012). "CRP, an acute-phase protein, shows elevated serum levels in CRC patients; in a study of 164 CRC patients, 34 with adenomas, and 119 healthy controls, CRP achieved an AUC of 0.64, with 17% sensitivity and 90% specificity, indicating limited diagnostic utility alone." (PMID 41294737, 2025). "The blood levels of CRP, sCD26 and TIMP-1 showed statistically significant differences between CRC patients and neoplasm-free participants, and levels of TIMP-1 were furthermore significantly elevated in advanced adenoma patients." (PMID 22454079, 2012). "Second, all adenomas were analysed as whole group: The sensitivity for the combination of CEA + IL-8 was 18% (95%CI: 7-35%) and 15% (95%CI: 5-31%) for the combination of CEA + CRP, (both at a specificity of 86% (95%CI: 73-94%))." (PMID 22954206, 2012). "For the combination of CEA + CRP, non-advanced adenomas were detected with a sensitivity of 17% (95%CI: 2-48%) and advanced stage adenomas with 14% (95%CI: 3-35%) (all at a specificity of 86% (95%CI: 73-94%))." (PMID 22954206, 2012). "The combination of CEA + IL-8 recognized two of 12 non-advanced and five of 22 advanced adenomas and the combination of CEA + CRP detected also two of 12 non-advanced and three of 22 advanced adenoma patients correctly." (PMID 22954206, 2012). "In our study, high-sensitivity C-reactive protein level was significantly higher in MetS subjects with adenoma than in MetS subjects without polyps." (PMID 20507579, 2010).
bone metastasis (19 papers, 2006 to 2025). Transfer of a neoplasm from its primary site to bones. "Variations in TPINP levels showed significant associations with the presence of bone metastasis, basic disease, smoking history, T staging, CRP levels, NMID, β-CTX, IBI, and status." (PMID 40224215, 2025). "Univariate analysis showed that bone metastasis was associated with PFS and that staging, bone metastasis, and CRP were associated with OS, in the inosine group." (PMID 39267574, 2024). "Our study indicated that serum CRP was an independent risk factor for bone metastasis and SRE in patients with advanced RCC at cut-off value >84 U/L (p=.021), and the sensitivity and specificity was 75.9% and 85.5% respectively at ROC analysis." (PMID 37489216, 2023). "Diffuse type classification, bone metastasis, high neutrophil/lymphocyte ratio, and high CRP were associated with poor OS/prognosis in the multivariate analysis." (PMID 34845844, 2022). "High MTV was significantly associated with distant metastases (especially, bone metastasis), CRP, and PD-L1 expression ≥ 75%." (PMID 32929123, 2020). "A high MTV was significantly associated with distant metastases (especially bone metastasis), C-reactive protein (CRP) level, and PD-L1 expression ≥ 75%." (PMID 32929123, 2020). "The risk factors ECOG status, serum LDH, serum levels of CRP, and presence of bone metastasis were further integrated into a multivariate Cox regression model." (PMID 31722735, 2019). "Patients with cytoreductive nephrectomy, bone metastasis, high C-reactive protein levels and paraneoplastic symptoms were significantly correlated with short progression-free survival in the univariate analysis." (PMID 38651176, 2024). "score encompassing ALP, CRP, Hb, and ESR are potential risk factors for developing SRE and concomitant bone metastasis in advanced RCC patients." (PMID 37489216, 2023). "Although multiple factors were involved in the prognosis of mCRPC with bone metastasis, CRP tended to be higher in patients with a poor prognosis according to multivariate analyses." (PMID 34148264, 2021). "According to multivariate analysis, the factors independently associated with PFS were ECOG PS (HR 1.37, 95% CI 1.02-1.84, P = 0.035), bone metastasis (HR 1.74, 95% CI 1.14-2.65, P = 0.009), and CRP elevation (HR 1.64, 95% CI 1.28-2.09, P = 0.001)." (PMID 22103888, 2011). "In addition to the histological parameters, we identified that the serum levels of ALP, CRP, Hb and ESR are directly associated with bone metastasis." (PMID 37489216, 2023). "Second, given the difficulty in evaluating bone metastasis, the relationship between CRP and chemotherapy response is still unknown." (PMID 24130817, 2013). "The cut-off values of ALP, CRP, Hb and ESR for the prediction of bone metastasis were >236 U/ml (AUC .849, p=.01), >84 μg/ml (AUC .856, p=.021), <10.5 g/l (AUC .765, p=.045) and 74 mm/hour (AUC .880, p=.032), respectively." (PMID 37489216, 2023). "On the multivariate logistic regression analysis calculated to determine bone metastasis along with SREs, the odds ratio (OR) for serum ALP (95% CI) was 2.48 (1.49-4.02), p=.001, while the same for CRP (95% CI) was 2.28 (1.08-4.81), p=.029." (PMID 37489216, 2023). "The areas under the ROC curve for ALP, Hb, CRP, and ESR were 0.84, 0.76, 0.86 and 0.88, respectively, suggesting excellent discriminatory capability of ALP, CRP, ESR and sufficient discriminative ability of Hb in predicting bone metastasis." (PMID 37489216, 2023). "Patients without cytoreductive nephrectomy and with bone metastasis, liver metastasis, high C-reactive protein levels and paraneoplastic symptoms were significantly correlated with shorter progression-free survival." (PMID 38651176, 2024). "Univariate analysis revealed that factors associated with inferior OS included male, age ≥ 62 years old, current or former smoker, liver metastasis, bone metastasis, low ChE at baseline (p = 0.004), a reduction level of ChE (p < 0.001), low ALB, high CRP and high SAA." (PMID 38730286, 2024).